CD4 (CD4 molecule)
Diseases named in the same sentence as CD4 in open-access papers (continued):
Sharing a sentence is not in itself a finding about the gene and the disease.
emphysema (continued). "Using Cuzick’s test of trend, there was also a significant trend towards higher severity of emphysema (0–5 scores) in lower CD4/CD8 ratio groups (p = 0.02)." (PMID 28122034, 2017). "In a second multivariable model, now with additional adjustment for CD4 count and HIV viral load as continuous variables, those with CD4/CD8 ratio <0.4 remained at higher risk for emphysema (OR 7.4, 95% CI 1.5–35) compared to those with CD4/CD8 ratio >1.0." (PMID 28122034, 2017). "Those with CD4/CD8 ratio <0.4 had 6.3 (1.1–39) times the odds of >10% emphysema compared to those with a ratio >1.0 in fully adjusted models." (PMID 28122034, 2017). "We also found a significant trend towards higher severity of emphysema in those with lower CD4/CD8 ratios." (PMID 28122034, 2017). "In conclusion, in our cohort of HIV+ subjects we found an independent association of a low peripheral blood CD4/CD8 ratio with radiographic emphysema and a low DLCO that is likely reflective of pulmonary parenchymal loss in emphysema." (PMID 28122034, 2017). "Our primary aim in this study was therefore to determine the association between CD4/CD8 ratio and radiographic emphysema." (PMID 28122034, 2017). "In adjusted analyses among those with viral load suppression, those with CD4/CD8 <0.4 (n = 36) were estimated to have 20 times the odds (95% CI 2.5–153) of emphysema." (PMID 28122034, 2017). "The additional significant finding of the independent association of a low CD4/CD8 ratio and DLCO provides further evidence of a link with emphysema." (PMID 28122034, 2017). "In multivariable logistic regression analyses adjusting for demographics, smoking, BMI, chronic diseases and drug use, those with CD4/CD8 ratio <0.4 had 6.0 (95% CI 1.6–22) times the odds of >10% emphysema compared to those with CD4/CD8 ratio >1.0." (PMID 28122034, 2017). "Emphysema is more prevalent in HIV, and has been associated with markers of systemic inflammation and immunosuppression (nadir CD4 cell count <200) in HIV+ patients." (PMID 28122034, 2017). "For instance, cytotoxic T cells (CD8+ T cells) are involved in emphysema development through the release of different cytotoxic substances, while CD4+ T cells release cytokines and chemokines increasing and perpetuating the inflammatory process." (PMID 29326759, 2017). "Another study has also demonstrated decreased CD4+CD25+ Treg cell number in lung tissue from emphysema patients, which in turn correlated with FOXP3 mRNA expression." (PMID 27178410, 2016). "In this study, we employed a rat model of chronic cigarette smoking-induced inflammation and emphysema to test the impact of BMSCs on the lung inflammation and injury, CD4+ T cell infiltration in the lung, and humoral responses to elastin." (PMID 26665150, 2015). "We found that basal levels of mRNA transcripts for IL-10 and IFN-γ in lung CD4+ T cells were unrelated in individual subjects, and were inversely correlated with emphysema extent vs. spirometry, respectively." (PMID 24805101, 2014). "To confirm the presence of autoreactive elastin-specific T cells, we used freshly isolated CD4+ T cells from control and emphysema volunteers and determined the relative abundance of elastin tetramer positive T cells." (PMID 22969766, 2012). "We developed a dual cytokine enzyme-linked immunocell spot assay, the γ-6 Spot, using CD4 T cell IFN-γ and IL-6 responses and found that it discriminated emphysema with 90% sensitivity." (PMID 22969766, 2012). "In contrast, CD46 down regulation was associated with decreased FEV1%, decreased expression of CD95 and CD4+ T cell depletion concomitantly with CD8+T cells increase in lung parenchyma of emphysema/COPD patients." (PMID 21573156, 2011). "Others have suggested that humoral- and CD4+ cell- dependent mechanisms can lead to alveolar septal cell apoptosis and the development of emphysema." (PMID 16571143, 2006).
emphysema (continued). "Intraperitoneal injection of endothelial cells led to the production of antibodies against endothelial cells, influx of CD4+ T cells in the lung, alveolar septal apoptosis, activation of matrix metalloproteinases and the development of emphysema." (PMID 16571143, 2006). "We extend these findings by showing CXCR3 expression on lung macrophages and CD4+ T cells in emphysema patients and the functional interplay between Th1-related chemokines and elastolytic MMPs." (PMID 15526056, 2004). "Together, these two independent datasets provided evidence that the emphysema variant of COPD is characterized by the positive enrichment of αβ CD4 T cells and negative enrichment of pulmonary macrophages." (PMID 40993192, 2025). "Indeed, nCB-emphysematous let7bc2LOF mice exhibited enhanced RORγt protein levels in both CD8+ and CD4+ T cells relative to control mice with emphysema." (PMID 38722677, 2024). "Consequently, we selected mice exposed to tobacco for 12 weeks to evaluate the expression of Tim3 and NFIL3 in CD4+ T cells during the early stages of emphysema." (PMID 39555065, 2024). "In support of our original hypothesis, the CD4+ T cell expression of Mirlet7a, Mirlet7b, Mirlet7d, and Mirlet7f were all inversely correlated with more severe emphysema distribution in the lungs as determined by Computed Tomography (CT) scan." (PMID 38722677, 2024). "In our study, we also demonstrated that mice with emphysema induced by chronic tobacco exposure exhibited significantly higher CD4 expression in the lung microenvironment, alongside abnormal activation of CD4+ Tem cells, with Th1 cells showing a differentiation advantage." (PMID 39555065, 2024). "We hypothesize that CD4 + T-cell-dependent mechanisms may trigger the development of alveolar septal cell apoptosis and experimental emphysema." (PMID 37880804, 2023). "However, there has been little study into the mechanism of MSC administration on CD4+ T cells in the pathogenesis of emphysema." (PMID 36012176, 2022). "We observed a decrease in CD4+ lymphocytes in the spleen of mice with PPE-induced emphysema." (PMID 36012176, 2022). "Oligoclonal expansion of CD4+ T cells in lung tissue of emphysema patients has been shown and immune responses against elastin as a component of lung tissue have been supported by increased production levels of IFNγ from peripheral blood CD4+ T cells in COPD patients." (PMID 34271910, 2021). "In the same study, an independent association between a low peripheral CD4/CD8 ratio (<0.4) and emphysema was found, suggesting that residual immune activation may contribute to the pathogenesis of emphysema in PLWH." (PMID 33936110, 2021). "(2009) showed that human lung DCs isolated from subjects with advanced emphysema could differentiate CD4+ T cells into distinct effector subsets." (PMID 34956243, 2021). "Additionally, they found that patients with a nadir CD4+ T cell count <200 cells/mL had 2 times greater odds of having increased emphysema (OR 2.39; 95% CI 1.02, 5.62)." (PMID 31830103, 2019). "The anatomic distribution of emphysema was similar between groups of CD4/CD8 ratio as was pattern of emphysema (i.e. centrilobular, panlobular and with or without paraseptal emphysema), with the majority of subjects with >10% emphysema having diffuse centrilobular disease involving all lobes." (PMID 28122034, 2017). "The association between mean HU attenuation values across the three vertebrae and radiographic emphysema, age, sex, body mass index (BMI), steroid use, viral load, CD4 count, and forced expiratory volume in the first second (FEV1) was assessed by univariate and multivariate analyses." (PMID 28448615, 2017). "We demonstrate that the peripheral blood CD4/CD8 ratio, as a marker that may reflect residual immune activation in HIV, is associated with radiographic emphysema in our cohort of HIV+ subjects." (PMID 28122034, 2017).
emphysema (continued). "A low CD4/CD8 ratio was associated with emphysema and low DLCO in HIV+ subjects, independent of other risk factors and clinical markers of HIV." (PMID 28122034, 2017). "The CD4/CD8 ratio may be a useful, clinically available, marker for risk of emphysema in HIV+ subjects in the antiretroviral therapy (ART) era." (PMID 28122034, 2017). "Importantly, we demonstrated for the first time that IL-27R (WSX-1) was upregulated on naïve CD4+ T cells in the setting of cigarette smoke-induced emphysema, which absence on effector T cells." (PMID 27994590, 2016). "In addition, cigarette smoke exposure dramatically upregulated the expression of IL-27R (WSX-1) by naive CD4+ T cells in a mouse model of emphysema." (PMID 27994590, 2016). "However, the frequency of functional CD4+ T cells in the lungs of individuals with COPD particularly during the early process of chronic smoking-related emphysema and their cytokine and chemokine production in the lungs have not been systemically investigated." (PMID 26665150, 2015). "Therefore, we assessed the relative abundance of tetramer positive CD4+ T cells following 3 days of culture with EFs in controls and emphysema volunteers." (PMID 22969766, 2012). "We found that while some CD4+ T cells in emphysema had increased relative abundance of elastin positive tetramers without any stimulation, in most cases, up to 10-fold increase in T cell binding to the tetramers was found following 3 days of T cell stimulation with EFs (B and Figure A6 in Appendix)." (PMID 22969766, 2012). "We found that there is a large spectrum of the concentration of cytokine secreted by CD4 T cells in response to EFs, but ever-smokers with emphysema largely continued to show robust T cells responses to EFs that both persisted and increased significantly when compared to the initial response." (PMID 22969766, 2012). "Importantly, our findings demonstrate that, irrespective of lung function status, the presence of elastin-specific CD4+ T cells in the peripheral blood correlates with the degree of emphysema." (PMID 22969766, 2012). "However, when cultured in vitro, we found seven major CD4-expressing TCR-Vbeta subset expansions from five of the patients with emphysema." (PMID 21162738, 2010). "In addition, IL21 produced by CD4+ T cells could promote a Th1/Tc1 response, leading to systemic inflammation in emphysema." (PMID 38612871, 2024). "Additionally, in their HIV+ study arm, low CD4 T-cell counts and high soluble CD14 levels were linked with disease severity, supporting the notion that immune activation in PLWH contributes to the risk of pulmonary emphysema development." (PMID 35058937, 2021). "We were most interested in the association between the CD4/CD8 ratio and emphysema because increasing evidence suggests that emphysema, linked to chronic inflammation in the general population, may be particularly associated with residual inflammation in those with HIV." (PMID 28122034, 2017). "Neither nadir CD4 count nor sCD14 maintained a significant association with emphysema." (PMID 28122034, 2017). "The peripheral blood CD4/CD8 ratio may serve as a marker of chronic immune activation, and may be clinically useful in identifying HIV+ individuals at risk for chronic lung disease related to increased inflammation, particularly emphysema." (PMID 28122034, 2017). "Therefore, we sought to determine whether the CD4/CD8 ratio was associated with chronic obstructive pulmonary disease (COPD), particularly the emphysema subtype, in a cohort of HIV+ subjects." (PMID 28122034, 2017). "We identified significant independent correlations of levels of unstimulated mRNA transcripts in lung CD4+ T cells with specific COPD phenotypes: reduced IL-10 transcripts were associated with emphysema, whereas pervasive absence of T-cell polarization was associated with airflow obstruction." (PMID 24805101, 2014).
emphysema (continued). "However, to further pinpoint the specific epitopes and because of the consistently higher responses seen in groups 1 and 5, CD4+ T cells from those with emphysema were subsequently stimulated with individual overlapping 20-mer peptides within the amino acids 1–100 and 401–500." (PMID 22969766, 2012). "Furthermore, mice deficient in CD8+ T-cells are resistant to cigarette smoke induced emphysema whereas CD4+ T-cell deficient mice are not." (PMID 21647421, 2011). "The increase of CD4+, CD8+ cells expressing NF-κB, STAT4, IFN-γ and perforin are related to smoking habit, smoking history, airflow rate, obstruction and pulmonary emphysema." (PMID 38903812, 2024). "It has been documented that CD4+ and CD8+ lymphocytes infiltrate the airways of COPD patients correlating positively with high alveolar destruction (emphysema) and airway obstruction." (PMID 37108906, 2023). "The T-cell immune responses disorders in the intestinal tract were further supported by immunohistochemistry analysis, wherein fewer CD4-positive cells and more CD8-positive cells were found both in the small intestine and colon of emphysema mice." (PMID 36052717, 2022). "Administration of MSCs to subjects with severe emphysema resulted in increased CD31 expression, and CD3+ and CD4+ T cells, but the significance of these changes in the context of emphysema pathogenesis remains elusive." (PMID 33580031, 2020). "After adjusting for CD4 count and HIV viral load, individuals with a CD4/CD8 ratio <0.4 had 7.4 times the odds of >10% emphysema compared to those with a CD4/CD8 ratio >1.0 (OR 7.4, 95% CI 1.5, 35)." (PMID 31830103, 2019). "In our emphysema model, both one and two doses of MSCs mitigated BALF CD4+ T cell count; however, only the two-dose regimen showed a reduction in percentage of total lymphocytes." (PMID 30409216, 2018). "In particular, percentages of CD4+ and CD8+ T lymphocytes as well as CD4+CD25+Foxp3+ (i.e., Treg) cells were investigated, since emphysema can lead to an imbalance in lymphocyte subpopulations." (PMID 30409216, 2018). "The median CD4/CD8 ratio for those with >10% emphysema was 0.38 (IQR 0.25–0.59), compared to 0.54 (IQR 0.33–0.88) (p = 0.03) for those with ≤10% emphysema." (PMID 28122034, 2017). "It has also been shown that the CD4+ INF-γ producing cells were related to the degree of airway obstruction, and that the CD4+ T cells from smokers with emphysema showed a Th17 profile, as they were able to secrete IL-17A." (PMID 28536707, 2017). "Subjects with lower CD4/CD8 ratio were more likely to have >10% emphysema: 43% of those with CD4/CD8 ratio <0.4 had emphysema, compared to 25% of those with CD4/CD8 ratio 0.4–1.0 and 21% of those with CD4/CD8 >1.0 (p = 0.03 for χ2 test)." (PMID 28122034, 2017). "Smoking status, smoking history, degree of airflow obstruction and pulmonary emphysema are all related to increased CD8+ cells and/or CD8+/CD4+ ratio." (PMID 27178410, 2016). "Emphysema patients had an increased number of ICI (CD20, CD3, CD8, CD68, CD45RO, CD4 and PMN) as compared with controls (p ≤ 0.01)." (PMID 15705190, 2005). "The infiltrated tissue around bronchioles that has been characterized in COPD patients showed the presence of CD4+ and CD8+ lymphocytes correlating with histologic lesions suggestive of emphysema, and clear signs of airway obstruction and cell destruction due to the release of perforins and TNFα." (PMID 37108906, 2023). "The authors demonstrated that total CD4+ T cells from PBMC that were cocultured with CD1a+ from lungs of subjects with advanced emphysema, but not control subjects, secreted higher amounts of IFN-γ and IL-17A." (PMID 34956243, 2021). "The addition of markers previously associated with emphysema in our cohort, nadir CD4 cell count and sCD14, to the model did not attenuate the association between CD4/CD8 ratio and emphysema (OR 6.3, 95% CI 1.1–39 for CD4/CD8<0.4 compared to CD4/CD8>1.0)." (PMID 28122034, 2017).
emphysema (continued). "In a larger cohort, it may have been possible to demonstrate a more robust relationship between the CD4/CD8 ratio and our secondary outcomes, specifically low FEV1 and airflow obstruction, which were less common in our study compared to emphysema and low DLCO." (PMID 28122034, 2017). "The CD4/CD8 ratio is thought to reflect residual inflammation and immune activation in HIV+ patients, and may be correlated with emphysema in HIV by way of these mechanisms, which may persist despite ART." (PMID 28122034, 2017). "HIV+ subjects with CD4/CD8 ratio between 0.4–1.0 did not have significantly different odds of emphysema compared to those with a higher ratio in any of these models." (PMID 28122034, 2017). "Despite the inhibitory activity of IL-27 on the secretion of IL-17 by naive CD4+ T cells in vitro, IL-27 neutralization did not lead to a more exaggerated IL-17 production in smoking mouse model of emphysema." (PMID 27994590, 2016). "Inflammatory markers such as CRP were not elevated in emphysema progressors, nor were emphysema progressors more likely to have lower CD4 cell counts, lower CD4:CD8 ratios, or detectable HIV viral loads." (PMID 27902753, 2016). "In mice, CS-exposure induces lung recruitment of CD4+, CD8+, and B cells, enhancing pro-inflammatory Th1 cytokine production that might significantly contribute to emphysema development." (PMID 25962837, 2015). "CD4 T-cell IFN-gamma production was also uniquely increased in rGRP78-supplemented cultures and, again, especially so in the preparations from subjects with emphysema." (PMID 25216103, 2014). "While CD4+ T lymphocyte-defecient mice are not at all protected, CD8+ T lymphocyte-deficient mice are 100% protected against emphysema following mainstream exposure." (PMID 23720629, 2013). "We have previously reported a positive correlation between increase in IFN-γ and IL-10, but not IL-4 or IL-13, responses to EFs from CD4+ T cells isolated from former smokers with emphysema severity." (PMID 22969766, 2012). "It remains however, unclear if ART should be considered in all HIV infected patients with proven emphysema or bronchiectasis, independent of CD4 count and clinical staging." (PMID 17888170, 2007). "Similar to other previously published studies, we were able to demonstrate that peripheral blood CD4/CD8 ratios is not decreased in emphysema, illustrating some degree of discordance between lung and peripheral blood." (PMID 17822550, 2007). "T cells specified as CD4+ and CD8+ T lymphocytes have been recently shown to be critical for the induction of inflammation, secretion of pro-inflammatory mediators, tissue destruction, and activation of other immune cell types (B cells) in a murine model of smoke-induced emphysema." (PMID 38979411, 2024). "Moreover, CD4+ T cells cultured with CD1a+ DCs from control, but not emphysema, differentiated into Treg cells, evidenced by an up-regulation of Foxp3 expression." (PMID 34956243, 2021). "We hypothesized that a low CD4/CD8 ratio would be associated with emphysema and with pulmonary function markers of COPD, independent of other markers including the current and nadir CD4 cell count." (PMID 28122034, 2017). "We suggest that these findings may indicate that systemic inflammation and immune activation, reflected by a low CD4/CD8 ratio, may lead to increased parenchymal destruction that is characteristic of emphysema, however, this would require further investigation." (PMID 28122034, 2017). "Consistently, in this much larger cohort using a CD4+ T cells to APCs ratio (10:1), we found a strong positive correlation between the production of IFN-γ (r = 0.59, P < 0.0001) and IL-6 (r = 0.58, P < 0.0001), and the severity of emphysema as determined by quantitative CT scan." (PMID 22969766, 2012). "Therefore we measured CD4+ T cell cytokine responses to EFs 10–24 months following the first assay in randomly selected ever-smokers with (n = 45) or without (n = 32) emphysema." (PMID 22969766, 2012).